TIPARP (TCDD inducible poly(ADP-ribose) polymerase)
Description:
ADP-ribosyltransferase that mediates mono-ADP-ribosylation of glutamate, aspartate and cysteine residues on target proteins. Acts as a negative regulator of AHR by mediating mono-ADP-ribosylation of AHR, leading to inhibit transcription activator activity of AHR.
Synonyms: ARTD14; PARP-7; PARP7; DKFZP434J214; DKFZp686N0351; DDF1; PARP-1; pART14; RM1
Tractability: Small molecule: a high-quality ligand is known. PROTAC: ubiquitination databases record sites on it; a small molecule that binds it is known.
Target class: Enzyme; Transferase
Chemical probes: ATAMPARIB (high quality)
Gene: Protein-coding gene on chromosome 3 (156,673,235 to 156,706,770, forward strand). Ensembl gene ENSG00000163659.
Subcellular location: Nucleus
Subcellular location (Human Protein Atlas): Microtubules
Gene Ontology:
Molecular function: cis-regulatory region sequence-specific DNA binding; NAD+ poly-ADP-ribosyltransferase activity; NAD+-protein mono-ADP-ribosyltransferase activity; NAD+-protein-aspartate ADP-ribosyltransferase activity; NAD+-protein-cysteine ADP-ribosyltransferase activity; NAD+-protein-glutamate ADP-ribosyltransferase activity; metal ion binding
Biological process: negative regulation of gene expression; positive regulation of protein catabolic process; protein auto-ADP-ribosylation; response to 2,3,7,8-tetrachlorodibenzodioxine
Cellular component: nucleus
Genetic constraint (gnomAD): Loss-of-function variants: 12 observed, 56.24 expected, observed/expected ratio (o/e) 0.21, 90% interval 0.14 to 0.35. The upper end of that interval is the gene's LOEUF score, 0.35, which puts it in group 1 of 6, group 1 being the genes least tolerant of losing a copy. Missense variants: 604 observed, 817.83 expected, observed/expected ratio (o/e) 0.74, 90% interval 0.69 to 0.79. Synonymous variants: 296 observed, 281.16 expected, observed/expected ratio (o/e) 1.05, 90% interval 0.96 to 1.16.
Homologues: Orthologues: macaque TIPARP (99% identical), chimpanzee TIPARP (99% identical), pig TIPARP (96% identical), dog TIPARP (95% identical), guinea pig TIPARP (94% identical), mouse Tiparp (93% identical), rat Tiparp (92% identical), rabbit TIPARP (83% identical), tropical clawed frog tiparp (62% identical), zebrafish tiparp (18% identical). Paralogues in human: PARP12 (25% identical), ZC3HAV1 (21% identical), PARP14 (18% identical), PARP11 (15% identical), PARP15 (14% identical), PARP10 (12% identical), PARP9 (10% identical), ZC3HAV1L (5% identical).
Diseases named in the same sentence as TIPARP in open-access papers:
TIPARP is named in the same sentence as 70 diseases in open-access papers, as found by Europe PMC text mining. Sharing a sentence is not in itself a finding about the gene and the disease. The quoted sentences say what the papers report.
breast cancer (27 papers, 2014 to 2026). A primary or metastatic malignant neoplasm involving the breast. "In contrast, in colorectal cancer and breast cancer, the high expression of TIPARP has been reported to be associated with a favorable prognosis." (PMID 36841751, 2023). "Assay 4 also includes 3334 primer probes selecting 1701 SNPs within 1 Mb of the TIPARP locus and the exons of 46 genes associated with breast cancer." (PMID 24782526, 2014). "We also observed associations of borderline significance with the TIPARP rs2665390 polymorphism, which was previously found to be associated with ovarian and breast cancer, and with the EXOC1 rs13117307 polymorphism, which has been linked to cervical cancer in a large study in a Chinese population." (PMID 28505207, 2017). "In this study, our risk model based on TIPARP, SAMD4A, TSEN54, GSPT2, and RNASE1 was compared with the high and low risk groups of breast cancer cell lines in the CellMiner database." (PMID 36911389, 2023). "In the case of TIPARP, we found that in agreement with previous reports on breast cancer cells, expression levels were increased by E2 (pretreated vs. non-pretreated cells) and apparently by R5020 as well (treated vs. untreated conditions)." (PMID 35018885, 2022). "In line with our results, higher TIPARP expression has been reported to be related to better survival in breast cancer." (PMID 34552928, 2021). "Assay 4 also targets 1701 individual SNP positions on the flanking regions of the TIPARP locus and the exons of 46 additional genes involved in breast cancer." (PMID 24782526, 2014). "TIPARP act as a tumor suppressor in breast cancer that might be regulated by DNA methylation." (PMID 34434692, 2021). "Consistent with the trend of results from public databases, TSEN54 was upregulated in breast cancer cell lines and GSPT2, RNASE1, SAMD4A, and TIPARP were downregulated in breast cancer cell lines." (PMID 36911389, 2023). "Although TIPARP as a candidate therapeutic target in OA cartilage is novel, this RBP has been suggested as a therapeutic target in breast cancer." (PMID 37457300, 2023). "GSPT2, SAMD4A, and TIPARP are downregulated in ECM-receptor interaction pathways, which play important roles in tumor shedding, adhesion, degradation, motility, and proliferation and may be involved in breast cancer development." (PMID 36911389, 2023).
ovarian carcinoma (19 papers, 2014 to 2025). A malignant neoplasm originating from the surface ovarian epithelium. "Regarding the relationship between cancer and the expression of TIPARP, the high expression of TIPARP has been reported to be associated with a poor prognosis and invasion in ovarian cancer." (PMID 36841751, 2023). "TIPARP (the gene encoding PARP-7, located at 3q25) was identified in a susceptibility locus for ovarian cancer in a recent genome-wide association study." (PMID 33475085, 2021). "Recent genome wide association studies (GWASs) have shown that TIPARP is a susceptibility locus for ovarian cancer, namely, an intergenic SNP was highly significantly associated (P = 1.5 × 10–28) with ovarian cancer risk although the potentially causal variants remain unknown." (PMID 24782526, 2014). "In a study on ovarian cancer, knockdown of TIPARP was reported to reduce cell growth, migration, and invasion in OVCAR4 cells." (PMID 36536086, 2022). "TIPARP knockdown reduces ovarian cancer cell growth and motility partly through the ADP-ribosylation of α-tubulin." (PMID 34129049, 2021).
prostate carcinoma (14 papers, 2016 to 2025). A carcinoma that arises from epithelial cells of the prostate gland. "PARP7 expression in primary prostate cancer tumors is correlated with both AHR and AR, which is not surprising given the TIPARP gene is a direct target of both transcription factors." (PMID 37077937, 2023).
lung carcinoma (12 papers, 2014 to 2026). "Using the assay, we found that the overexpression of TIPARP in lung cancer cells enhanced angiogenesis." (PMID 36841751, 2023). "Ribon Therapeutics recently presented a potent and selective small molecule inhibitor of TIPARP (PARP7), referred to as RBN-2397 that enhances IFN-I signaling and causes lung cancer regression in xenograft models." (PMID 34129049, 2021). "Further studies on TIPARP in lung cancer are expected to be conducted in the future." (PMID 36841751, 2023). "Moreover, the elevated expression of TIPARP in lung cancer may induce angiogenesis by remodeling the ECM." (PMID 36841751, 2023). "Since there are no reports of its association with lung cancer-angiogenesis, we investigated whether TIPARP is involved in the enhancement of angiogenesis by the introduction of three lung cancer-related factors using CAM assay." (PMID 36841751, 2023). "Furthermore, there are no reports on the relationship between the expression of TIPARP and invasion and angiogenesis in lung cancer." (PMID 36841751, 2023).
viral infection (9 papers, 2019 to 2025). "TIPARP is involved in several biological processes including innate immunity, responses to viral infection, stem cell pluripotency, astrocyte autophagy, and the regulation of transcription." (PMID 31083300, 2019). "TIPARP expression is induced by platelet-derived growth factors, viral infection, nuclear hormone receptors and AHR." (PMID 31083300, 2019).
colon cancer (7 papers, 2014 to 2024). "RBN-2397-mediated TIPARP inhibition prevents CT26 colon tumor growth in a type I IFN signaling dependent manner." (PMID 34129049, 2021).
cerebral infarct (3 papers, 2020 to 2023). "Moreover, circHECTD1 promoted autophagy by regulating the miR-142/TIPARP pathway, leading to the loss of neurons and the neurological impairment in mice with cerebral infarction." (PMID 32639948, 2020). "In addition, circHECTD1 suppression can also significantly reduce cerebral infarct size in mice with transient middle cerebral artery occlusion through the MIR142/TIPARP pathway, reduce neuronal damage, and promote the activation of astrocytes." (PMID 37968257, 2023). "In tMCAO mice, the knockdown of circHectd1 can significantly decrease cerebral infarct size, neuronal deficits, and astrocyte activation, though miR-142 targets TCDD inducible poly[ADP-ribose] polymerase (TIPARP) and inhibits the astrocyte activation via macroautophagy/autophagy." (PMID 36329693, 2022).
glioma (3 papers, 2022 to 2025). A benign or malignant brain and spinal cord tumor that arises from glial cells (astrocytes, oligodendrocytes, ependymal cells). "The results revealed a positive correlation between the expression of genes such as ZC3HAV1, TIPARP, PARP4, PARP14, and PARP15 and the abundance of various immune cell types in gliomas." (PMID 39724285, 2024). "The authors analyzed by microarray the transcriptome of kynurenine-treated glioma and found an AHR signature, characterized by an upregulation of AHR-target genes such as CYP1B1 (Cytochrome P450 family 1 subfamily B member 1) and TIPARP (TCDD-inducible poly-ADP-ribose polymerase)." (PMID 36188218, 2022).
papillary thyroid carcinoma (3 papers, 2024 to 2025). "TIPARP is a prognostic biomarker and potential immunotherapy target for male papillary thyroid carcinoma." (PMID 41453319, 2025). "TCGA data analyzed through XENA tools showed TIPARP mRNA was upregulated in male papillary thyroid carcinoma (PTC) with lymph node metastasis (LNM) versus without (AUC 0.692), indicating potential as a diagnostic biomarker." (PMID 38233939, 2024).
squamous cell carcinoma (3 papers, 2021 to 2025). A carcinoma arising from squamous epithelial cells. "TIPARP is found in PM 2.5-exposed A549 cells, and the TIPARP locus region on chromosome 3 (3q25) is frequently amplified in squamous cell carcinoma." (PMID 36841751, 2023).
Stroke (3 papers, 2020 to 2025). Sudden impairment of blood flow to a part of the brain due to occlusion or rupture of an artery to the brain. "CircHectd1 acts as an endogenous RNA sponge and binds miR-142 to promote astrocytic autophagy via the downstream target TIPARP (TCDD inducible poly [ADP-ribose] polymerase), resulting in astrocyte activation in stroke." (PMID 35720192, 2022).
thyroid cancer (2 papers, 2025). "In contrast, genes such as TCDD-inducible poly (ADP-ribose) polymerase (TIPARP) and Glutaminyl-peptide cyclotransferase (QPCT), exhibited overexpression in thyroid carcinoma." (PMID 40346322, 2025).
asthma (1 paper, 2022). "PCR analysis showed that mRNA expression of BPIFA2 and ENPEP was upregulated in both asthma and COPD, while the expression of CYP1B1-AS1 and TIPARP was increased in the epithelium from COPD patients only." (PMID 36012391, 2022). "We showed that the most potently activated genes after air pollution exposure in the triple co-cultured epithelium of asthma and COPD patients were BPIFA2 and ENPEP, while CYP1B1-AS1 and TIPARP were upregulated in the COPD epithelium only." (PMID 36012391, 2022).
Cerebral ischemia (1 paper, 2022). Restriction of arterial blood supply to the brain associated with insufficient oxygenation to support the metabolic requirements of the tissue. "CircHECTD1 is significantly elevated in brain tissues after cerebral ischemia and acts as a sponge of endogenous miR-142 to inhibit its activity, thereby upregulating the expression of TCDD inducible poly(ADP-ribose) polymerase (TIPARP) and promoting autophagy." (PMID 36110390, 2022).
diabetes (1 paper, 2023). "Additionally, TIPARP expression can be induced by metformin which is in clinical use for the treatment of diabetes." (PMID 37457300, 2023).
Hypertension (1 paper, 2021). The presence of chronic increased pressure in the systemic arterial system. "This is supported by the present observations, which demonstrated that CKD-induced hypertension coincides with the activation of the AhR signaling pathway as represented by increased ARNT and TIPARP expression." (PMID 35052587, 2021).
nonalcoholic fatty liver disease (1 paper, 2021). "As examples, the present commentary tries to integrate responses of AHR and NAD+-consuming enzymes (PARP7/TiPARP, CD38 and sirtuins) into infectious and stress-induced inflammatory responses, the latter exemplified by nonalcoholic fatty liver disease (NAFLD)." (PMID 34559251, 2021).
Nystagmus (1 paper, 2020). Rhythmic, involuntary oscillations of one or both eyes related to abnormality in fixation, conjugate gaze, or vestibular mechanisms. "The fact that two proteins, CYP1A1 and TiPARP, are not induced in the heterozygous patients who lack the Nystagmus phenotype, indicate that these genes are not involved disease development." (PMID 33193710, 2020). "The fact that CYP1A1 and TiPARP genes are not induced upon BA-activation of AHR in the heterozygotes, who do not exhibit the nystagmus phenotype, might suggest that their gene products are not involved in the ocular pathology observed in the homozygous patients." (PMID 33193710, 2020).
primary open angle glaucoma (1 paper, 2022). "The expression of TIPARP was significantly upregulated in the blood and trabecular meshwork of patients with primary open angle glaucoma compared with that of healthy controls." (PMID 36536086, 2022).
wasting syndrome (1 paper, 2021). "Characterizing the TCDD-induced TIPARP ADP-ribosylated proteome will be important to fully understand the increased sensitivity of TiparpH532A mice, and may also provide new insight into TCDD-induced toxicity and wasting syndrome." (PMID 34129049, 2021).
tumor (58 papers, 2014 to 2026). "Moreover, we unveiled co‐occurrence relationships among ITSGs in tumour mutations, such as TIPARP with DDX3X and HERPUD1 with DNAJB1." (PMID 39031800, 2024). "Among the eight significant mutated genes, CDK12, CTNNB1, and MLH1 were tested in both tumor and blood, whereas CTCF, IGF1R, IKBKE, QKI, and TIPARP were only tested in tDNA." (PMID 40227722, 2025). "RNA-seq identified robust induction of xenobiotic metabolism (CYP1A1, CYP1B1), oxidative/metabolic stress mediators (GDF15, TIPARP), and tumour-associated genes (FOSB, VGF), alongside repression of tumour suppressors (FAT1, LINC00472)." (PMID 41600570, 2025). "In some models, TIPARP inhibitors show persistent tumor growth suppression, potent antiproliferative effects, and restored interferon signaling." (PMID 38233939, 2024). "We used qRT-PCR to measure the relative mRNA expression levels of four risk genes (TIPARP, SERPINA3, MT1M, and CST2) in the normal prostate tissue cell RWPE-1 and in different tumor cell states such as LNCaP and C4-2 cell lines." (PMID 37346077, 2023). "Although TIPARP exhibits opposing effects in different tumor cells, in general, TIPARP is involved in the regulation of tumor cells by estrogen and is a potential target for the study of anti-tumor drugs." (PMID 37907864, 2023). "Although the exact function of TiPARP is presently unclear, its effects on T-cell function and its possible contribution to tumor promotion suggest a role also in the normal or arthritic synovial membrane." (PMID 24690414, 2014). "Finally, we assessed correlations between TIPARP expression, immune infiltration, and the tumor microenvironment." (PMID 38233939, 2024). "Notably, TIPARP was highly expressed in the tumor relative to the normal group expression, and CD24, TACC1, HSD17B10, and CAV1 were less expressed in the tumor relative to the normal group." (PMID 37907864, 2023). "TIPARP acts as a tumor inhibitor by down-regulating pro-tumor transcription factors." (PMID 36911389, 2023). "Conversely, TIPARP knockdown promotes tumor growth in an MCF-7 xenograft model." (PMID 34129049, 2021). "More recently, PARP7, a mono-ART also known as TCDD-inducible poly-ADP-ribose polymerase (TIPARP), has emerged as a critical regulator of tumour progression by promoting cancer cell growth and suppressing antitumor immunity." (PMID 41432900, 2025). "TIPARP directly targets HIF-1α and recruits E3 ubiquitin-protein ligase to promote the degradation and inactivation of HIF-1α to inhibit tumor growth." (PMID 37907864, 2023). "For example, the AhR-target PARP7 (product of the gene TIPARP), can directly suppress STING activity by facilitating the degradation of TBK1, a key downstream effector kinase of STING, thereby suppressing IFN-I expression and subsequent anti-tumor immunity." (PMID 38459088, 2024). "Tumor mutational burden (TMB) serves as a biomarker for immunotherapy response in some cancers, but TIPARP did not correlate with TMB." (PMID 38233939, 2024).
cancer (41 papers, 2021 to 2026). A tumor composed of atypical neoplastic, often pleomorphic cells that invade other tissues. "Emerging evidence proposes TIPARP activation as an anti-cancer approach, with its inhibition stimulating cancer cell and immune effects via enhanced IFN signaling." (PMID 38233939, 2024). "Multiple studies indicate that TIPARP plays important roles in the regulation of gene expression, innate immunity, interferon signaling, and cancer." (PMID 34129049, 2021). "The dysregulation of TIPARP may induce neuronal developmental disorders, abnormal antiviral responses, some types of cancer, and dioxin-induced steatohepatitis." (PMID 36536086, 2022). "TIPARP has recently emerged as a potential therapeutic target for cancer treatment." (PMID 34129049, 2021). "Thus, the functions of TIPARP are not well understood, as it may depend on the cancer characteristics." (PMID 36841751, 2023). "In addition, TIPARP has been identified as a potential target of cancer therapy." (PMID 36536086, 2022). "This implies that TIPARP’s effects on cancer may be context and cancer type specific." (PMID 34129049, 2021). "However, the mechanism though which TIPARP induces angiogenesis in cancer remain unclear." (PMID 36841751, 2023). "Recently, chemical genetics using targeted TIPARP mutation and NAD+ analogs have been used to characterize the TIPARP (PARP7) ADP-ribosylated proteome in HEK293, ovarian (OVCAR4) cancer cells and HeLa cells." (PMID 34129049, 2021). "TIPARP has both cancer intrinsic effects and extrinsic effects via its inhibitory role in type I interferon (IFN) signaling, and because of this it has emerged as a potential therapeutic target for cancer treatment." (PMID 34129049, 2021).
neurologic disorders (1 paper, 2019). "Moreover, TIPARP was identified as a highly upregulated protein following trace fear conditioning and in neurologic disorders, such as epilepsy." (PMID 31704703, 2019).
TIPARP also shares sentences with these, for which no sentence is quoted: infection (8 papers); lung adenocarcinoma (4); colorectal cancer (3); kidney cancer (3); metastatic tumors (3); pancreatic cancer (3); prostate tumors (3); cervical cancer (2); prostate adenocarcinoma (2); ulcerative colitis (2); adenocarcinoma (1); androgen insensitivity syndrome (1); antisynthetase syndrome (1); autoimmune disease (1); Autoimmunity (1); bacterial infection (1); breast tumors (1); capillary malformation (1); cardiovascular disease (1); cervical squamous cell carcinoma (1); colitis (1); colorectal adenocarcinoma (1); diffuse large B-cell lymphoma (1); dwarfism (1); epithelial ovarian tumors (1); esophageal cancer (1); experimental autoimmune encephalomyelitis (1); glioblastoma (1); Hepatic steatosis (1); immune diseases (1).
A further 17 diseases each share a sentence with TIPARP in 1 paper.